CXCR4 (C-X-C motif chemokine receptor 4)
Diseases named in the same sentence as CXCR4 in open-access papers (continued):
Sharing a sentence is not in itself a finding about the gene and the disease.
hematological malignancies (61 papers, 2010 to 2026). "In analogy with hematologic malignancies, high CXCR4 expression in solid tumors is associated with worse prognosis." (PMID 30105558, 2018). "Bruton's tyrosine kinase (BTK) and the chemokine receptor CXCR4 are linked in various hematologic malignancies." (PMID 25083818, 2014). "In hematological malignancies, several clinical trials using CXCR4 antagonists or targeting CXCR4 have also been conducted, but some completed clinical trials (NCT01120457, NCT04274738, NCT01236144, NCT01010880) have not posted experimental results." (PMID 40626005, 2025). "A notable example is NOX-A12 (also known as olaptesed pegol), a Spiegelmer aptamer that targets CXCR4 and has been primarily investigated in CXCR4+ hematological malignancies." (PMID 40307933, 2025). "While CXCR4-targeted radionuclide therapies such as 177Lu/90Y Pentixather have shown promise in hematological malignancies, bone marrow toxicity remains a limitation in solid tumors due to high radiotracer uptake." (PMID 40075611, 2025). "Plerixafor (AMD3100) is a specific CXCR4 inhibitor approved by the Food and Drug Administration (FDA, USA) as a CXCR4-targeted therapy for hematopoietic stem cell mobilization in hematological malignancies." (PMID 40075611, 2025). "In hematological malignancies, CXCR4 is thought to function less in chemotactic migration and more as a retention signal that keeps malignant cells within the bone marrow where they are protected from chemotherapy." (PMID 39253415, 2025). "While CXCR4 is physiologically expressed by numerous hematological and immune cells, its overexpression is well documented in hematological malignancies and various lymphomas." (PMID 39595051, 2024). "CXCR4-targeted RLT has already achieved durable response including partial or complete remission in patients with hematological malignancies." (PMID 38082196, 2024). "The CXCR4-targeting PET agent [68Ga]-Pentixafor has been administered to patients with various hematologic malignancies, allowing the identification of patients who can be treated with the therapeutic CXCR4-targeting radiotracer [90Y]/[177Lu]-Pentixafor." (PMID 39325320, 2024). "Beyond conferring survival advantages to malignant cells, the activated CXCL12/CXCR4/ACKR3 axis also enhances the invasiveness of hematological malignancies by regulating cell migration and conferring resistance to chemotherapy." (PMID 38920657, 2024). "The surface expression of C-X-C chemokine receptor type 4 (CXCR4) is up-regulated in some hematological malignancies including NHL." (PMID 38464386, 2024). "In line with this trait, several solid cancers and hematologic malignancies exhibit CXCR4 upregulation on the cell surface, and radiotracer accumulation was shown to correlate with immunohistochemical CXCR4 expression of corresponding tissue samples." (PMID 36672341, 2023). "C-X-C motif chemokine receptor 4 (CXCR4) is a G-protein coupled receptor that can be found in many hematological malignancies as well as solid tumors and constitutes a possible theranostic target." (PMID 38256859, 2023). "Recent years, however, have witnessed an increasing evaluation of CXCR4-directed imaging and therapy in particular for patients with hematological malignancies, thereby expanding this theranostic concept towards hemato-oncology." (PMID 37286923, 2023). "CXCR4 overexpression has been demonstrated in patients with hematologic malignancies, solid cancers, as well as cardiovascular pathologies of inflammatory origins." (PMID 36749409, 2023). "CXCR4 was shown to have high expression in many hematological malignancies, and multiple solid cancers, which is also related to poor prognosis." (PMID 36272970, 2022). "The present review will provide an overview of current applications for CXCR4-directed molecular imaging and will introduce the CXCR4-targeted theranostic concept for advanced hematological malignancies." (PMID 35674738, 2022).
hematological malignancies (continued). "The therapeutic approach of utilizing CXCR4 inhibition to combat hematological malignancies is separately discussed under the section “Targeting the niche”." (PMID 36568151, 2022). "The effects of anti-CXCL12/CXCR4 therapies have been most extensively studied in hematological malignancies, in which monoclonal CXCR4 targeting antibodies such as Ulocuplumab, have been tested with varying results." (PMID 33530455, 2021). "Actually, there are two fully human anti-CXCR4 antibodies—PF-06747143 and ulocuplumab —used for the treatment of hematologic malignancies." (PMID 32260318, 2020). "The molecular mechanisms regulating the expression of CXCR4 in hematological malignancies have therefore been largely investigated." (PMID 32432042, 2020). "Ulocuplumab is a fully humanized anti-CXCR4 monoclonal antibody with a longer half-life than plerixafor, which shows pro-apoptotic activity in the context of hematological malignancies." (PMID 32260318, 2020). "The mechanisms that regulate the expression of CXCR4 in hematologic malignancies have therefore been the focus of intense investigations." (PMID 30787933, 2019). "Despite histological evidence in various solid tumor entities, available experience with CXCR4-directed diagnostics and endoradiotherapy mainly focuses on hematologic diseases." (PMID 31475113, 2019). "Collectively, we have demonstrated that CXCR4 inhibition by LY2624587 has the potential for the treatment of human hematological malignancies." (PMID 26954567, 2016). "Another concern about CXCR4 antagonism as a treatment strategy in hematologic malignancies is the prospect of mobilizing leukemic cells from the bone marrow to other sites and contributing to disease spread." (PMID 26360610, 2015). "Our paper is the first demonstration of the efficacy of the novel CXCR4 antagonist POL5551 in hematologic malignancies." (PMID 26360610, 2015). "Proof of concept for efficient CXCR4 inhibition has been demonstrated in stem cell mobilization prior to autologous transplantation in hematological malignancies." (PMID 24058588, 2013). "Considering the promising results that have been obtained with CXCR4-directed radioligand therapy in hematological malignancies, the same approach could potentially be applied to solid tumor patients with sufficient CXCR4 expression on PET." (PMID 39355052, 2023). "Last, we focused on MZL, as relative to others, this type of hematological malignancy has been well characterized by CXCR4-directed imaging including superiority to standard diagnostic work-up, indicative for a more widespread use in patients with MZL in the near-term future." (PMID 37286923, 2023). "For instance, the small molecule CXCR4 inhibitor Plerixafor exhibits potential for mobilizing hematopoietic stem cells, and the inhibition of CXCL12/CXCR4 signaling may serve as an adjuvant in the treatment of hematologic malignancies and solid tumors." (PMID 37679744, 2023). "Beyond hematologic malignancies, CXCR4 overexpression has been described in various solid cancers." (PMID 34885030, 2021). "Patients who are eligible for CXCR4-directed radioligand therapy may be treated with β-emitters such as 177Lu/90Y-PentixaTher, and this approach has been used successfully mainly in the clinical settings of hematological malignancies." (PMID 39355052, 2023). "Moreover, we describe a link between iron metabolism and CXCR4 in the hematological malignancies which may suggest a potential mechanism through which leukemic cells acquire a metastatic phenotype and a tendency to move to a distal organ." (PMID 32432042, 2020). "Therefore, inhibition of CXCR4 by LY2624587 may represent a potential treatment option for patients with hematological malignancies." (PMID 26954567, 2016). "While preclinical experiments implicate CXCR4 antagonism as a promising means of chemosensitizing AML and other hematologic malignancies, clinical results have shown limited efficacy." (PMID 39253415, 2025).
hematological malignancies (continued). "Currently, clinically approved drugs targeting chemokines include anti-CCR4 antibodies (Mogamulizumab) and CXCR4 antagonists (Plerixafor, AMD3100), which are utilized in the treatment of hematological malignancies." (PMID 39691368, 2024). "Ulocuplumab, a completely human IgG4 anti-CXCR4 antibody, able to inhibit CXCL12 binding to its receptor, has shown promise in preclinical research and early-stage clinical trials for various hematological malignancies." (PMID 39198407, 2024). "CXCR4 monoclonal antibodies, including ulocuplumab, PF-06747143, LY2624587, are mainly used in the treatment of hematological malignancies." (PMID 37497001, 2023). "PF-06747143, a humanized anti-CXCR4 immunoglobulin G1 (IgG1) antibody, is used to fight hematological malignancies and also inhibit downstream pathways activated by the CXCL12/CXCR4 axis." (PMID 36293358, 2022). "The C-X-C chemokine receptor 4 (CXCR4, CD184) appears to be one of the most promising targets in hematologic malignancies and some solid tumors." (PMID 35158894, 2022). "Phase I trials are ongoing to evaluate the safety and tolerability of the anti-CXCR4 mAbs BMS-936564 in AML patients (NCT01120457) and PF-06747143 in hematological malignancies (NCT02954653)." (PMID 30894861, 2019). "Examining the expression level of CXCR4 has recently been considered for the development of a PET-based imaging technique and subsequent quantitative evaluation of blood disorders and tumors, including LPDs since this receptor is overexpressed in various blood cells and solid tumors." (PMID 38792485, 2024). "Since CIML NK cells are being used for the treatment of hematological malignancies (clinical trials NCT01898793, NCT03068819, and NCT02782546), it would be preferable that they express higher levels of CXCR4 in order to improve the trafficking to the bone marrow." (PMID 29713323, 2018). "Thus, in the context of hematological malignancies, we analyzed the expression of CD62L and CXCR4, two cell surface receptors that are required for homing to lymph nodes and bone marrow, respectively." (PMID 29713323, 2018). "Targeted disruption of the CXCR4-CXCL12 and VLA4-VCAM1 axes with CXCR4 or VLA4 antagonists has been explored to enhance the efficacy of chemotherapy against both hematological (acute myeloid leukemia, acute and chronic lymphoid leukemia, and multiple myeloma) and non-hematological malignancies." (PMID 39199390, 2024). "Among multiple CXCR4 inhibitors available for research, only AMD3100 (also known as plerixafor) has been approved for the induction of autologous hematopoietic stem cell (HSC) mobilization in patients with hematological malignancies (see ‘targeting the niche’)." (PMID 36568151, 2022). "Additionally, the development of improved monoclonal antibodies targeting molecules involved in the trafficking of MM, CLL, and ALL cells, such as CXCR4, CD44, SLAMF7/CS1, and CCR9 might open new opportunities for clinical treatments against these hematologic malignancies." (PMID 30787933, 2019).
adenocarcinoma (20 papers, 2006 to 2025). A common cancer characterized by the presence of malignant glandular cells. "In one approach, pH-sensitive nanoliposomes were covalently decorated with the SDF1α protein, the natural ligand of CXCR4, to encapsulate and target the marine-derived drug Yessotoxin into CXCR4+ prostate and adenocarcinoma cells." (PMID 40307933, 2025). "The quantitative expressions of CXCL12 and CXCR4 messenger RNA (mRNA) were evaluated in 32 patients with adenocarcinoma-type CRC." (PMID 29887884, 2018). "Further studies are required in order to investigate the predictive value of VEGFR-3 and CXCR4 in terms of chemotherapeutic regimes in patients with advanced adenocarcinoma of the stomach and the gastroesophagic junction." (PMID 24981311, 2014). "Further studies are required in order to investigate the predictive value of VEGFR-3 and CXCR4 in terms of chemotherapeutic regimes in patients with advanced adenocarcinoma of the stomach and GEJ." (PMID 24981311, 2014). "On immunohistochemical staining using anti-human CXCR4 mouse monoclonal antibody (clone 44716) and anti-human/mouse CXCL12/SDF-1 mouse monoclonal antibody (clone 79018), DLBCL cells were positive for CXCR4 and adenocarcinoma cells were positive for CXCL12/SDF-1." (PMID 34187383, 2021). "Notably, positive expression of CXCR4 was observed in all epithelial cells of adenocarcinoma, which is consistent with previous observations." (PMID 18349830, 2008). "Notably, positive expression of CXCR4 was observed in all epithelial cells of adenocarcinoma." (PMID 18349830, 2008). "The adenocarcinoma marker cytokeratin-7 (CK7) and CXCR4 IHC staining further verified the liver lesions as adenocarcinoma that exhibited CXCR4 expression." (PMID 35145271, 2022). "They observed that the expression levels of Bcl-2 and bcl-xl in the adenocarcinoma cell line increased with CXCL12 therapy and decreased with CXCR4 antagonist and JAK2 inhibitor therapy." (PMID 31718601, 2019). "Of the 71 tissues, 65 had uniformly detectable CXCR4 immunostaining; 6 samples displayed a proportion (<30%) of adenocarcinoma cells without undetectable CXCR4." (PMID 19352387, 2009).
cardiovascular diseases (20 papers, 2011 to 2025). "Literature review revealed that SELP and PECAM1 are associated with angiogenesis and cardiovascular diseases, while CXCR4, IL2RG, and CD48 are primarily involved in immune responses." (PMID 40612110, 2025). "As α-gal IgE sensitization has been shown to associate with CAD, we further explored roles of CCR6 and CXCR4 in cardiovascular disease." (PMID 35097011, 2021). "The chemokine receptor CXCR4 is a promising target for molecular imaging of CXCR4+ cell types, e.g. inflammatory cells, in cardiovascular diseases." (PMID 29967943, 2018). "In addition to these tracers, [68Ga]Ga-pentixafor, a radiopharmaceutical targeting the C-X-C chemokine receptor type 4 (CXCR4), has emerged as a promising tool for imaging inflammatory and ischemic processes in cardiovascular diseases." (PMID 40143163, 2025). "Platelet receptors ACKR3 and CXCR4 play a crucial role in a variety of cardiovascular diseases." (PMID 39373210, 2025). "Although recent studies have demonstrated that CXCL12/CXCR4 axis plays a critical role in lymphocytes and macrophages’ recruitment to the sites of injury in diverse cardiovascular diseases, while its effect in AF is unknown." (PMID 34453039, 2021). "It is possible that miR-9-5p/CXCR4 axis may play a broader role in pathological conditions such as cardiovascular disease and neurological diseases, where endothelial cells are also vital for the initiation and progression of the disease." (PMID 33977146, 2021). "Due to the importance of SDF-1/CXCR4 axis in the stem cell and progenitor cell survival and function, understanding this axis and molecules that modulate their production and action will be of utility for the treatment of cardiovascular disease." (PMID 26441982, 2015). "There are a number of clinically approved drugs, including DPP4 inhibitors and parathyroid hormone, which have the ability to enhance SDF-1/CXCR4 responsiveness and may improve the outcome of cardiovascular diseases." (PMID 26441982, 2015). "In addition, intravenous delivery of mesenchymal stem cells (MSCs) overexpressing CXCR4 improves cardiac function and remodeling after MI, suggesting CXCR4 as an important therapeutic target for the treatment of cardiovascular diseases." (PMID 22039399, 2011). "Receptors such as CXCR4, CXCR5, and ACKR3 not only direct B-cell trafficking but also influence their phenotype in cardiovascular disease." (PMID 40986007, 2025). "Because systemic administration of plerixafor is associated with adverse effects, especially to patients with cardiovascular diseases, further development of CXCR4-tropic HIV-1 entry inhibitors with weaker affinity to CXCR4 than plerixafor is needed." (PMID 32154191, 2020). "Since the ratio of circulating non-infectious to infectious virions is exponentially greater, the role played by these non-infectious virus particles in the progression to cardiovascular disease cannot be ignored, particularly in cell expressing the CXCR4 chemokine receptor." (PMID 25329893, 2014).